POU2F2 (POU class 2 homeobox 2)
Diseases named in the same sentence as POU2F2 in open-access papers (continued):
Sharing a sentence is not in itself a finding about the gene and the disease.
triple-negative breast carcinoma (1 paper, 2020). An invasive breast carcinoma which is negative for expression of estrogen receptor (ER), progesterone receptor (PR), and human epidermal growth factor receptor 2 (HER2). "The antisense transcript of nicotinamide phosphoribosyltransferase (lncRNA NAMPT-AS) recruits POU class 2 homeobox 2 (POU2F2) to activate the transcription of NAMPT, in order to further promote tumor progression and autophagy in triple-negative breast cancer through the mTOR pathway." (PMID 32429086, 2020).
tumor (34 papers, 2015 to 2025). "Recent studies have shown that POU2F2 acts as tumor-promoting roles in some cancers, but the underlying mechanism remains little known." (PMID 33931589, 2021). "Other major potential tumor growth factors, such as POU2F2, RUNX1, ERG, REL, and JUN, were also relatively increased in the low TEX-score group." (PMID 38629071, 2024). "The results showed that the mRNA and protein expression levels of SLC2A3 were significantly increased in tumor tissues, while the expression level of POU2F2 was significantly decreased in tumor tissues." (PMID 38026928, 2023). "POU2F2 localized to the cytoplasm and nucleus in tumor tissues, but was mainly found in the cytoplasm in paracancerous tissues." (PMID 37733361, 2021). "Immunoblot assays provided the evidence that the expression of AGO1 in POU2F2-depleted tumor tissues were obvious decrease compared with that in control, consistent with the previous data." (PMID 33832481, 2021). "POU2F2 expression was significantly increased in tumor samples from patients compared with normal tissues from individuals with no cancer." (PMID 33931589, 2021). "The expression scores of POU2F2 and the ratio of nuclear POU2F2+ cells were significantly increased in tumor tissues compared with paracancerous tissues." (PMID 37733361, 2021). "The subcutaneous xenograft models further confirmed that POU2F2 promoted tumor growth in a PDPK1 dependent manner." (PMID 33931589, 2021). "The B-cell specific TF POU2F2 was predicted to inhibit tumor cell apoptosis and enhance transcription, and IRF4 in combination with ATF6 was predicted to play an important role in the development of hematopoietic neoplasm." (PMID 32585984, 2020). "The majority of our insertions at the Pou2f2 locus are intragenic, consistent with the tumor suppressor function observed in FL." (PMID 29985390, 2018). "Further, analysis of sequencing data from MMRF‐CoMMpass found that POU2F2, RUNX1, and RUNX2 gene mutations were relatively rare (1.36%, 2.09%, and 0.83%, respectively) among MM patients compared to other tumor types profiled in TCGA, suggesting that their functions are preserved in MM." (PMID 40167268, 2025). "Tumor-infiltrating CD4+ T cells (C12_CD4) were associated with binding motif enrichment for cluster-specific TFs such as members of the POU domain family (POU2F1, POU2F2 and POU2F3), in addition to TF programs shared with dysfunctional CD8+ T cells." (PMID 35668194, 2022). "And the tumor weight in POU2F2-depleted groups was also decreased markedly comapred to control." (PMID 33832481, 2021). "In our study, POU2F2 appears to be a tumor suppressor in ADC." (PMID 29127420, 2017). "However, the role of POU2F2 in regulating tumor progression remains controversial." (PMID 33931589, 2021). "Although the initial CCM screen evaluated associations with a gene signature of immune activity, including TLS formation, the emerging CCMs covered genes that are expressed by tumor cells (e.g., RSAD2, CMPK2) and stromal fibroblasts (e.g., SUCNR1) as well as immune cells (e.g., POU2F2)." (PMID 40723216, 2025). "The TFs that appeared more than four times in tumor samples were defined as malignant tumor-conservative TFs including Fral, KLF5, and NFY, while TFs that appeared only once were defined as specific TFs such as POU2F2." (PMID 34722892, 2021). "Additionally, we further found POU2F2 ablation suppressed the expression of Ki67, PCNA, and N-cadherin in tumor tissues, suggesting the inhibition of tumor growth." (PMID 33832481, 2021). "Given that NANOG is a core pluripotent TF that induces tumor stemness, POU2F2 induces NANOG expression alone may initiate POU2F2+ hepatocytes to acquire stemness." (PMID 37733361, 2021).
cancer (31 papers, 2011 to 2025). A tumor composed of atypical neoplastic, often pleomorphic cells that invade other tissues. "Originally identified as a B-cell specific transcription factor, POU2F2 has also been implicated in several other cancer cell lineages as well." (PMID 35213597, 2022). "ARID1A was highly expressed in cancer cell and fibroblasts, POU2F2 was significantly expressed in cancer cell, and SPI1 was highly specific to myeloid cell, suggesting its involvement in immune regulation." (PMID 40396172, 2025). "For instance, HMGB1, HMGB2, and MS4A1 were hypomethylated and highly expressed, whereas hypermethylation of genes such as LDB1, NDUFS2, and POU2F2 led to their reduced expression, reinforcing the impact of DNA methylation on gene dysregulation in cancer." (PMID 40396172, 2025). "The overexpression of POU2F2 is correlated with aggressive cancer phenotypes and unfavorable prognoses across various malignancies." (PMID 40167268, 2025). "G-CSF also formed a network with other proteins involved in cancer growth and progression, such as POU2F2, HEF1, and CXCL3." (PMID 39739128, 2024). "The identified TFs, such as FOXC1, FOXL1, POU2F2, NFIC, NFkB1, MEF2A, GATA2, and E2F1, are mainly associated with different types of cancers and congenital disorders." (PMID 37026010, 2023). "POU2F2 is thought to have a pro-oncogenic role in some cancers, but its role in CRC remains unclear." (PMID 38026928, 2023). "POU2F2 is highly expressed in some solid tumors and provides the prognosis of cancer patients." (PMID 33931589, 2021). "Finally, we selected a conservative TF kruppel-like factor 5 (KLF5) and malignant tumor-specific TF POU class 2 homeobox 2 (POU2F2) and analyzed their expression in each type of malignant tumor samples." (PMID 34722892, 2021). "Conservative TF KLF5 and specific TF POU2F2 were chosen to exhibit the expression of all malignant tumors through a beeswarm package, which also could distinguish malignant tumor-specific TFs from conservative TFs." (PMID 34722892, 2021). "Recently, the critical role of POU2F2 in the progression of cancers has been revealed in depth." (PMID 33832481, 2021). "Several previous studies provided the evidence that POU2F2 could serve as a promising therapeutic target and predict the poor prognosis of cancers." (PMID 33832481, 2021). "Consequently, the POU2F2/PTPRG-AS1/miR-376c-3p/SLC7A11 axis holds potential as both a novel biomarker and therapeutic target for ferroptosis-mediated cancer therapy in TNBC." (PMID 39867656, 2024). "Besides the genes encoding ZAPs, we also detected five genes encoding signaling molecules involved in the immune response to cancer, namely TRAF6, EIF2AK2, PIK3CA, APAF1, and POU2F2." (PMID 34844636, 2021).
infection (1 paper, 2021). The state of being infected such as from the introduction of a foreign agent such as serum, vaccine, antigenic substance or organism. "AAV8‐IL‐31, but not AAV8‐vector, infection also induced the development of POU2F2+ OCT4+, POU2F2+ SOX2+, and POU2F2+ NANOG+ hepatocytes at months 6 and 10 post‐DEN." (PMID 37733361, 2021). "The infection of AAV8‐IL‐31, but not AAV8‐vector, increased Pou2f2 mRNA and induced POU2F2+ hepatocytes development at months 6 and 10 post‐DEN, suggesting that hepatic IL‐31 recovery restores Pou2f2 expression." (PMID 37733361, 2021). "AAV8‐shNanog infection successfully suppressed NANOG expression as shown by non‐detection of hepatic Nanog mRNA, NANOG+ hepatocytes, and POU2F2+ NANOG+ hepatocytes at this time point, but it did not affect POU2F2+ hepatocytes production." (PMID 37733361, 2021).
POU2F2 also shares sentences with these, for which no sentence is quoted: leukemia (3 papers); pancreatic cancer (3); prostate carcinoma (3); hepatocellular carcinoma (2); acute kidney injury (1); acute lymphoblastic leukemia (1); astrocytoma (1); bladder cancer (1); clear cell renal cell carcinoma (1); colorectal adenocarcinoma (1); colorectal tumor (1); coronary artery disease (1); developmental delay (1); diabetes (1); endometrioid carcinoma (1); epilepsy (1); Ewing sarcoma (1); Guttmacher syndrome (1); head and neck squamous cell carcinoma (1); hematopoietic neoplasm (1); Huntington disease (1); hypospadias (1); Immunodeficiency (1); inflammatory bowel disease (1); large cell lymphomas (1); lung squamous cell carcinoma (1); medulloblastoma (1); metastatic prostate carcinoma (1); myeloid leukemia (1); Obesity (1).
A further 11 diseases each share a sentence with POU2F2 in 1 paper.